NF2 (NF2, moesin-ezrin-radixin like (MERLIN) tumor suppressor)
Diseases named in the same sentence as NF2 in open-access papers (continued):
Sharing a sentence is not in itself a finding about the gene and the disease.
anaplastic ependymoma (1 paper, 2018). Anaplastic ependymoma is a rare, malignant type of ependymoma that most often arises in the supratentorial region of the brain of children and young adults and that manifests with variable symptoms including headaches, nausea, vision impairment, memory loss and difficulty walking. "Spinal cord tumors were classified as: subependymoma (SP-SE), mixopapillary (SP-MPE) and anaplastic ependymoma (SP-EPN); in this group of tumors, only SP-EPNs display NF2 mutations or NF2 deletions." (PMID 30279357, 2018).
Angiomatous Meningioma (1 paper, 2014). A WHO grade I meningioma characterized by the presence of small and medium sized vessels that predominate over the meningioma cells. "To date, NF2 mutations have been described very infrequently in angiomatous meningioma, suggesting that the origin of angiomatous meningiomas is largely independent of NF2." (PMID 25347344, 2014).
Areflexia (1 paper, 2022). Absence of neurologic reflexes such as the knee-jerk reaction. "A previous study found hyperplasia of the DRG as an exclusive imaging and histological feature of NF2 that might serve as a potentially pathostructural correlate of areflexia and sensory loss in NF2-PNP." (PMID 35453828, 2022).
Ataxia (1 paper, 2024). Ataxia refers to impaired coordination of voluntary muscle movement. "In mice treated with anti-VEGF antibody, Nf2−/− tumor growth was inhibited, and the ataxia score remained unchanged over time." (PMID 38893082, 2024).
autoimmune disease (1 paper, 2023). A disorder resulting from loss of function or tissue destruction of an organ or multiple organs, arising from humoral or cellular immune responses of the individual to their own tissue constituents. "However, further experiments are needed to explore the functional role of NF2, FAM3B, and MGMT in BD and other autoimmune diseases." (PMID 37264476, 2023).
bone metastasis (1 paper, 2023). Transfer of a neoplasm from its primary site to bones. "Further analysis revealed cases with NF2 mutation detected from metastatic lesions were significantly associated with the presence of bone metastasis (80%, 4/5 vs. 21.4%, 3/14, P = 0.038)." (PMID 37131267, 2023). "The results showed that NF2 mutation may be associated with bone metastasis." (PMID 37131267, 2023).
brachial plexus tumor (1 paper, 2017). "Similarly, one case was described in parturient with NF2 who experienced an exacerbation of symptoms presumably due to an increase in size of a left brachial plexus tumor." (PMID 29245354, 2017).
breast tumor (1 paper, 2021). "We also performed RNAseq analysis of MCF10AT breast tumor cells stably silenced for NF2 (MCF10AT KD)." (PMID 33410252, 2021).
carcinosarcoma (1 paper, 2025). A malignant tumor composed of a mixture of carcinomatous and sarcomatous elements. "One recently published report on carcinosarcoma of the uterus identified an NF2 mutation alongside an ATM mutation; further information on the prevalence of NF2 in carcinosarcoma is needed." (PMID 40862839, 2025).
choroid plexus tumors (1 paper, 2016). "Moreover, whereas all 32 choroid plexus tumors in this series expressed NF2, three out of six papillary metastatic tumors were negative for NF2." (PMID 27229317, 2016).
cleft palate (1 paper, 2012). Cleft palate is a fissure type embryopathy that affects the soft and hard palate to varying degrees. "Here we provide the first description of clinical association between PRS (including cleft palate) and NF2 in a patient in whom we found a 22q12.2 deletion." (PMID 22436304, 2012). "Thus, our report describes a NF2-adjacent chromosome 22q12.2 deletion syndrome and is the first to report association of MN1 deletion with abnormal craniofacial development and/or cleft palate in humans." (PMID 22436304, 2012).
colitis (1 paper, 2024). Inflammation of the colon. "Furthermore, JAM-A-deficient mice also showed increased epithelial cell proliferation in colitis by interacting with tumor suppressor NF2, thus indicating the crucial role of JAM-A in intestinal homeostasis by attenuating permeability function and cell–cell contact in the intestine." (PMID 38791603, 2024).
cranial nerve tumors (1 paper, 2024). "Their broad developmental potential correlates with the broad range of tumor phenotypes in NF-2 patients, including spinal, peripheral and cranial nerve tumors." (PMID 39415595, 2024).
cyst (1 paper, 2016). A sac-like closed membranous structure that may be empty or contain fluid or amorphous material. "Thus Yap/Taz deletion from the UB epithelium leads to the opposite effect from loss of Nf2 and excess YAP, namely expanded expression of RET pathway/tip genes and cyst-like branching, that may represent unrestricted outward expansion of a tip fate." (PMID 27480037, 2016).
epithelioid mesothelioma (1 paper, 2023). "Noticeably, NF2 mutations are found more frequently in sarcomatoid rather than in epithelioid mesothelioma." (PMID 37180489, 2023).
follicular thyroid cancer (1 paper, 2020). "Chromosome 22q loss was associated with a widely invasive type of follicular thyroid cancer, and NF2 loss promotes RAS-induced tumorigenesis." (PMID 32380731, 2020).
gallbladder hydrops (1 paper, 2024). "This case report highlights the atypical presentation of symptomatic gallbladder hydrops in a 12-year-old girl, leading to the diagnosis of NF2 after the identification of a benign nerve sheath tumor involving the gallbladder." (PMID 39618887, 2024).
gastric tumor (1 paper, 2016). "Verteporfin suppressed liver tumor growth induced by YAP overexpression or NF2 inactivation in mice, and super-TDU suppressed growth of gastric tumor xenografts with Hippo pathway deregulation." (PMID 27144834, 2016).
gastrinoma (1 paper, 2014). "The possible pathogenic mechanisms underlying the dual development of gastrinoma and NF2 remain to be elucidated." (PMID 24961548, 2014). "Overall, the possible pathogenic mechanisms underlying the occurrence of both gastrinoma and NF2, which would allow to discriminate between an actual connection and a merely casual association, remain to be elucidated." (PMID 24961548, 2014).
gliosarcoma (1 paper, 2020). A rare histological variant of glioblastoma (WHO grade IV) characterized by a biphasic tissue pattern with alternating areas displaying glial and mesenchymal differentiation (WHO). "However, in our gliosarcoma patient with disease progression under entrectinib, no secondary NTRK mutation was detected, but molecular profiling revealed activation of alternative oncogenic pathways, including NF2 and insulin receptor (INSR)." (PMID 33353026, 2020).
hepatoblastoma (1 paper, 2023). Hepatoblastoma (HB) is a malignant hepatic tumor and is the most common pediatric liver cancer. "The tumor suppressive genes (Taok1, Lats1, Nf2), upstream of the Hippo pathway that inhibit YAP through phosphorylation-induced cytoplasmic retention and degradation, are important for hepatoblastoma proliferation." (PMID 37414763, 2023).
Hydrocephalus (1 paper, 2024). Hydrocephalus is an active distension of the ventricular system of the brain resulting from inadequate passage of CSF from its point of production within the cerebral ventricles to its point of absorption into the systemic circulation. "This is consistent with observations of hydrocephalus resulting from cerebrospinal fluid blockage in some NF-2 patients (Tanrıkulu and Özek, 2019)." (PMID 39415595, 2024).
hyperostosis (1 paper, 2021). Excessive thickening of bone. "While bone invasion was associated with NF2 mutations, hyperostosis was seen more often together with TRAF7 aberrations." (PMID 34800210, 2021).
keloid (1 paper, 2023). An irregularly shaped, elevated mark on the skin caused by deposits of excessive amounts of collagen during wound healing. "However, our results are innovative in revealing early wound healing-related genes (EPB41, TPM1, NF2, PARD3) in keloid patients from the perspective of alternative splicing regulated by RBP." (PMID 36777722, 2023).
macroglossia (1 paper, 2023). The presence of an excessively large tongue, which may be congenital or may develop as a result of a tumor or edema due to obstruction of lymphatic vessels, or it may occur in association with hyperpituitarism or acromegaly. "Our previous research has shown that Wnt1-Cre-mediated constitutive activation of Alk2 leads to microglossia, whereas the conditional knockout of Nf2 results in macroglossia during the early stages of embryonic development." (PMID 37680190, 2023).
Medullary thyroid carcinoma (1 paper, 2024). "Medullary thyroid carcinoma, which accounts for less than 10% of all thyroid malignancies, is associated with NF2 loss." (PMID 39796693, 2024).
metastatic carcinoma (1 paper, 2016). A carcinoma which has spread from the original site of growth to another anatomic site. "CP tumors of all grades could be differentiated from metastatic carcinomas with papillary architecture by NF2, which showed polarized membranous staining in CP tumors." (PMID 27229317, 2016).
Microcornea (1 paper, 2010). A congenital abnormality of the cornea in which the cornea and the anterior segment of the eye are smaller than normal. "For example, mutations in multiple genes have been associated with cataract plus microcornea (e.g., MAF, CRYAA, and GJA8), posterior polar cataract (e.g., PITX3, EPHA2, CHMP4B, and NF2), or sutural cataract (e.g., BFSP2, CRYAB, and NHS)." (PMID 21042563, 2010).
mononeuropathy (1 paper, 2023). Disease or trauma involving a single peripheral nerve in isolation, or out of proportion to evidence of diffuse peripheral nerve dysfunction. "A recognized feature of NF2 is mononeuropathy, particularly in childhood, which usually involves the facial nerve and can precede the development of other NF2 manifestations." (PMID 37217995, 2023).
multiple myeloma (1 paper, 2019). "These new targets to be considered in multiple myeloma treatment are the NOTCHs, BCL2, the IDHs, AR, NF2, Porcupine, the JAKs, MEK1/2 and the Aurora kinases." (PMID 31523388, 2019).
Myalgia (1 paper, 2025). "However, central in this core net one can find the genes NF2 and BRAF (associated to HPO-class BN and ACTH), EP300 (associated to HPO-class BN), AAAS (associated to HPO-class ACTH) and PTPN2 (associated to Myalgia)." (PMID 40831500, 2025).
myoepithelioma (1 paper, 2008). "The myoepithelioma of one of the patients carried an identical somatic rearrangement in the NF2 gene as the AT/RT, indicating that both tumours originated from a common precursor cell." (PMID 18087273, 2008).
myxoma (1 paper, 2025). A benign soft tissue neoplasm characterized by the presence of spindle and stellate cells, lobulated growth pattern, and myxoid stroma formation. "Further research is needed to investigate the potential risk of cardiac myxoma in patients with NF2 and the benefit of routine screening for myxomas in this population." (PMID 40713130, 2025). "•Although intracranial tumors are more common in patients with NF2, cardiac tumors, particularly myxomas, may also occur." (PMID 40713130, 2025).
neuroendocrine carcinoma (1 paper, 2024). A malignant neuroendocrine neoplasm composed of cells containing secretory granules that stain positive for NSE and chromogranin.
Osteoblastoma (1 paper, 2020). A rare benign bone-forming neoplasm usually arising from the spine. "Taken together, we show that NF2 loss characterises a subgroup of osteoblastomas, distinct from FOS‐rearranged cases." (PMID 32542935, 2020). "We found recurrent homozygous deletions of the NF2 gene in three of the five epithelioid cases and in one conventional osteoblastoma." (PMID 32542935, 2020). "Our main finding was complete loss of the NF2 gene in a subgroup of non‐FOS‐rearranged, preferentially epithelioid osteoblastomas." (PMID 32542935, 2020). "Both NF2 and FOS are involved in regulating bone homeostasis, thereby providing a mechanistic link to the excessive bone growth of osteoblastoma." (PMID 32542935, 2020).
osteoma (1 paper, 2008). A benign, well-circumscribed, bone-forming neoplasm predominantly composed of lamellar bone. "Other phenotypic abnormalities observed included osteomas at the adCre injection site, presumably induced by biallelic Nf2 inactivation in a neural crest precursor 4, 6, 17, and liver tumors." (PMID 17924978, 2008).
ovarian endometrioid carcinoma (1 paper, 2025). "WGS analyses revealed rearrangements involving PTEN, NF1, and NF2 in ovarian endometrioid carcinomas and NF1 and MED1 in ovarian mucinous carcinomas." (PMID 40981433, 2025). "Whole-genome sequencing revealed rearrangements involving PTEN, NF1, and NF2 in ovarian endometrioid carcinomas and NF1 and MED1 in ovarian mucinous carcinomas." (PMID 40981433, 2025). "These analyses revealed several novel rearrangements that were predicted to result in in-frame protein fusions in ovarian endometrioid carcinomas, including ATAD1–PTEN, the neurofibromin genes NF1 and NF2, as well as cyclin-dependent and polo-like kinase (PLK) genes CDK7 and PLK5." (PMID 40981433, 2025). "Rearrangements involving NF1 and NF2 have been reported in other cancers and have been associated with therapeutic resistance in HGSOC but have not been previously identified in ovarian endometrioid carcinoma." (PMID 40981433, 2025).
ovarian tumors (1 paper, 2020). "It served as an argument to weaken the case for ABCD4 and NF2 as oncogenic drivers of CABR18, given the discordant results found in her breast and ovarian tumors." (PMID 32295625, 2020).
pancreatic gastrinoma (1 paper, 2014). A neuroendocrine tumor arising from the pancreas. "We have reported the first case report of the association between NF2 and a pancreatic gastrinoma, although it remains to be determined whether this association is merely casual or not." (PMID 24961548, 2014). "The present case report refers to a woman with NF2 and a pancreatic gastrinoma." (PMID 24961548, 2014).
papilloma (1 paper, 2016). A benign epithelial neoplasm that projects above the surrounding epithelial surface and consists of villous or arborescent outgrowths of fibrovascular stroma. "The subcellular localization of moesin, ezrin and NF2 in CP papilloma was similar to that from normal CP." (PMID 27229317, 2016).
pericardial mesotheliomas (1 paper, 2025). "NF2 mutations are linked to peritoneal and pericardial mesothelioma too." (PMID 40725095, 2025).
poorly differentiated thyroid cancer (1 paper, 2024). "Additionally, NF2 loss in combination with HRAS mutation leads to murine poorly differentiated thyroid cancer (PDTC)." (PMID 39796693, 2024).
pulmonary fibrosis (1 paper, 2023). Chronic progressive interstitial lung disorder characterized by the replacement of the lung tissue by connective tissue, leading to progressive dyspnea, respiratory failure, or right heart failure. "We provide evidence that in response to bleomycin-induced pulmonary fibrosis, increased Taz through inactivation of Yap1, Stk3/4, or Nf2 is vital for AT1 cell differentiation and reduction of fibrosis." (PMID 37166104, 2023).
retina tumors (1 paper, 2024). "NF2 could be associated with retinal vasculopathy in addition to retina tumors." (PMID 38292257, 2024).
retinal detachment (1 paper, 2022). An eye emergency condition which may lead to blindness if left untreated. "Ophthalmologic anomalies led to an NF2 diagnosis for three children: one at age 2 years, with two retinal hamartomas diagnosed at age 1 year; one with retinal detachment at age 14 years resulting from congenital retinal hamartoma; and one because of posterior cataract at age 4 years." (PMID 35729665, 2022).
retinal ischemia (1 paper, 2024). A ischemic disease that involves the retina. "We reported an NF2 patient presenting with retinal ischemia." (PMID 38292257, 2024).
scoliosis (1 paper, 2012). A congenital or acquired spinal deformity characterized by lateral curvature of the spine. "Our data identify scoliosis and decreasing numbers of cutaneous schwannomas as risk factors for internal schwannomas in NF2." (PMID 22558206, 2012).
stomach adenocarcinoma (1 paper, 2015). "Examples include MST1/2 phosphorylation sites, MOB-binding domain, and the region critical for NF2 interaction; 3) In certain cancer types like stomach adenocarcinoma and uterine corpus endometrial carcinoma, mutation rates can be reasonably high (5.2%–5.9%)." (PMID 25482410, 2015).
subarachnoid hemorrhage (1 paper, 2018). A serious neurological disorder characterized by intracranial hemorrhage into the subarachnoid space. "Spontaneous subarachnoid hemorrhage (SAH) from a left pericallosal artery aneurysm occurred in a 17-year-old boy prior to diagnosis of NF2." (PMID 30250447, 2018).
supratentorial ependymoma (1 paper, 2022). A high grade ependymoma that is located within the supratentorial brain. "Although monozygosity of 22q has been reported in ~ 40% of RELA-fusion positive supratentorial ependymoma (ST-EPN-RELA), the rarity of pathogenic somatic NF2 variants in the majority of intracranial ependymoma suggests a different tumor suppressor gene to be located on chromosome 22." (PMID 36008825, 2022).
synovial sarcoma (1 paper, 2022). "However, NGS brought forth mutations atypical for synovial sarcomas, including cAMP-dependent protein kinase type I-alpha regulatory subunit (PRKAR1A) on chromosome 17q24.2 and a likely pathogenic mutation of the neurofibromin 2 (NF2) gene on chromosome 22q." (PMID 36380356, 2022).
tinea capitis (1 paper, 2017). "We note that one of our NF2-rearrranged cases was in association with prior low-dose radiation for a certain condition (tinea capitis), but larger studies and comparisons will be required to fully elucidate this." (PMID 28775249, 2017).
uveal melanoma (1 paper, 2015). A melanoma derived from melanocytes of the uveal tract. "In human tumors, failure to activate LATS1 due to either GNAQ mutations in uveal melanoma or through inactivation of NF2/merlin in the tumor-prone neurofibromatosis syndrome prevent this inhibitory signal and make YAP1 permissive for activation." (PMID 26549256, 2015).
viral infection (1 paper, 2024). "Although we see some caspase cleavage when we knock out NF2 and G6PD with sgRNAs, this is likely due to the viral infection since it is also present in the control cells treated with control sgRNA (lane 1)." (PMID 38879607, 2024).
Wilms tumor (1 paper, 2023). An embryonal neoplasm characterized by the presence of epithelial, mesenchymal, and blastema components. "NF2 GA frequency was highest in cdRCC (30%), sRCC (21%), uRCC (15%), and pRCC (12%) while lowest in ccRCC (3%), UC (3%) Wilms tumor (1%), and chRCC (0%)." (PMID 36917021, 2023).